EZH2 (enhancer of zeste 2 polycomb repressive complex 2 subunit)
Diseases named in the same sentence as EZH2 in open-access papers (continued):
Sharing a sentence is not in itself a finding about the gene and the disease.
tumor (continued). "Similarly, c-Myc also recruits HDAC3 and EZH2 to silence the expression of miR-29 that has been defined as a tumor suppressor." (PMID 24013378, 2013). "Significantly, EZH2 knockdown suppressed the angiogenesis and tumor growth of IBC cells in vivo." (PMID 24294976, 2013). "Interestingly SAHA activates tumor pathways, which are already deregulated in rhabdoid tumors (such as MYC, CYCLIND and the pluripotency associated program controlled by EZH2)." (PMID 23764045, 2013). "Moreover, we determined the effect of inhibition of GSK3β activity on EZH2 expression and tumor invasiveness in NPC cell lines in vitro." (PMID 23874688, 2013). "Importantly, we showed EZH2 knockdown significantly suppressed the tumor spheroid formation of FC-IBC-02S cells in suspension culture under ultra-low attachment culture condition, which is a characteristic of IBC cancer stem cells." (PMID 24294976, 2013). "EZH2 depletion led to cell cycle arrest at the G1/S transition, suggesting the protein may repress the tumor suppressing p27 gene." (PMID 23940717, 2013). "Moreover, depletion of EZH2 led to decreased tumor formation in a mouse xenograft model, consistent with the known role of EZH2 in the pathogenesis of other cancers." (PMID 23826629, 2013). "There are also reports demonstrating the crucial role of EZH2 in multiple tumours." (PMID 24351808, 2013). "Our results provide direct evidence that EZH2 is critical for the formation of tumor spheroids and invasion of human IBC cells and could be a potential target for developing novel therapeutic strategies for human IBC." (PMID 24294976, 2013). "We provide evidence to support that EZH2 is functionally active in SCLC tumours, exerts pro-tumourigenic functions in vitro, and is associated with aberrant methylation profiles of PRC2 target genes indicative of a “stem-cell like” hypermethylator profile in SCLC tumours." (PMID 23967231, 2013). "Consequently, the wild type EZH2 retained in these cells accounts for the generation of H3K27Me1 and H2K27Me2, which led to a global increase in H3K27Me3 by the mutant EZH2 in these tumor cells." (PMID 23494175, 2013). "Similarly, EZH2 has been reported to boost tumor growth by targeting signaling molecules that promote cellular differentiation and at the same time stimulating cell cycle progression." (PMID 23593167, 2013). "Similarly, PcG group proteins have been implicated in human carcinogenesis and some, including BMI1 and EZH2 are bona fide oncogenes that are overexpressed in many tumor types." (PMID 23673719, 2013). "Furthermore, UHRF1 and EZH2 have been proposed to synergistically promote inactivation of oncosuppressor genes, among which Nkx3.1 and Msmb, in tumor cells." (PMID 23675307, 2013). "Our findings indicate that GSK3β inactivation may account for EZH2 overexpression and subsequent tumour progression, and this mechanism might be a potential target for NPC therapy." (PMID 23874688, 2013). "This phenotype is linked to increased expression of the histone methyl transferase EZH2 (Enhancer of Zeste Homolog 2), which results in the down-regulation of the tumor suppressors Msmb and Nkx3.1 through increased methylation of lysine 27 of histone H3 (H3K27) on their promoter regions." (PMID 23675307, 2013). "EZH2 is critical for the formation of tumor spheroids and invasion of human IBC cells and could be a potential target for developing novel therapeutic strategies for human IBC." (PMID 24294976, 2013). "Moreover, spheroid-selected A431 cells express increased levels of stem cell markers, including Bmi-1, Sox2, Ezh2 and H3K27me3, and spheroid-selected A431 cells are highly efficient tumor forming cells." (PMID 24376802, 2013). "However, histologically normal epithelium showed weaker intensity and a lower percentage of EZH2 expression than did tumor tissue." (PMID 24266940, 2013).
tumor (continued). "Moreover, DZNep-induced inhibition of EZH2 dramatically diminished the number and self-renewal capacity of cancer cells with tumor-initiating properties and significantly decreased tumor xenograft growth and improved survival." (PMID 24345883, 2013). "Interestingly, EZH2 expression level in tumor tissue (dCt_Tumor) by itself is insufficient in predicting the prognosis of patient with NSCLC." (PMID 23300840, 2012). "EZH2 is a recently identified, key regulator of tumor angiogenesis." (PMID 23109879, 2012). "Downregulated miRNAs included miR-101, which is a tumor suppressor and inhibitor of EZH2." (PMID 23300583, 2012). "As the only known target gene of miR-26a, EZH2, acting as an oncogene, was shown to be involved in proliferation of different cell types, including tumor cell lines; it showed oncogenic activity and tumor transformation requiring histone methylatransferase activity." (PMID 23226446, 2012). "While we did not observe induction of cell cycle-associated tumor suppressor genes by silencing or pharmacological inhibition of EZH2, microarray analyses demonstrated a strong transcriptional reduction of the AXL receptor kinase." (PMID 23077658, 2012). "EZH2 is thought to promote tumor progression by silencing tumor suppressor genes." (PMID 23077658, 2012). "Recent findings implicate that EZH2 deregulation could be an important driver of tumour development and progression, and that inactivation of EZH2 may be therapeutically effective in many cancers." (PMID 22187039, 2012). "It is known that EZH2 is crucial in stem cell maintenance and tumour development." (PMID 22187039, 2012). "Also there was a significant increase in EZH2 in tumors with aGleason score >7 vs. <6 in addition to the significant positive correlation of EZH2 to TNM stage increasing with tumor progression." (PMID 22641253, 2012). "For this reason we investigated EZH2 expression in the most common other tumor types of liver." (PMID 22809481, 2012). "Blocking EZH2 expression or activity may represent a promising strategy for anticancer treatment targeting tumour cells, tumour endothelial cells and tumour stem cells." (PMID 22187039, 2012). "EZH2 promotes tumor angiogenesis by repressing the anti-angiogenic factor, Vash1." (PMID 24212967, 2011). "In this view, additional usage of DNMTs inhibitors in protocols targeting EZH2 might improve response in some tumor contexts." (PMID 21609503, 2011). "In turn, VEGF influences expression of the PcG protein, EZH2, in the tumor vasculature." (PMID 24212967, 2011). "Clinically, EZH2 expression increases with tumor grade and predicts poor prognosis." (PMID 24212632, 2011). "The goal of the present study was to assess whether STEAP and EZH2 could function as TAAs for LC, capable of generating anti-tumor CD4 T-cell responses." (PMID 22053850, 2011). "Further, several studies have shown oncogenic activity for EZH2 in a range of tumor cell types." (PMID 21941025, 2011). "Importantly, Ezh2 overexpression correlates with the pathological degrees and tumor progression of this cancer, suggesting its potential as a therapeutic target." (PMID 20478051, 2010). "EZH2 nuclear staining was present in tumor cores of 411 (79%) patients." (PMID 20920340, 2010). "The high proportion of RCCs showing increased EZH2 protein levels may also have therapeutic implications, since targeted inhibition of EZH2 expression has been shown to repress tumor cell growth." (PMID 20920340, 2010). "In metastasized RCCs, the risk of death for patients with EZH2 positive nuclei (> 5% up to 50%) was clearly enhanced above that for RCC patients who had no (0%) nuclear EZH2 staining in the tumor." (PMID 20920340, 2010). "Interestingly, EZH2 (located on 7q36.1) was frequently gained in basal-like tumours by aCGH (P = 0.004, Fisher's exact test), although no case of high-level amplification was observed." (PMID 20565864, 2010).
tumor (continued). "This “repressive” gene signature could be attributed to the dysregulated activation of epigenetic effectors like EZH2 by ETS factors leading to silencing of genes with potential anti-tumor activity." (PMID 20479932, 2010). "Finally, to prove that this interaction occurred also in clinical tumor specimens we performed ChIP to assess binding of ERG to the EZH2 promoter in ERGhigh and NoETS samples." (PMID 20479932, 2010). "In contrast, EZH2 protein expression was readily detected in 411 (79%) of the cancerous tissues, typically showing nuclear staining, without predominately staining of the central or peripheral zone of tumor." (PMID 20920340, 2010). "This may explain why tumours with high EZH2 respond poorly to therapy, in contrast to tumours with high BMI1." (PMID 19099573, 2008). "However, to our surprise, tumours with high EZH2 expression did have high INK4a/ARF expression in 33% of the cases." (PMID 19099573, 2008). "Moreover, we found inverse correlations for BMI1 and EZH2 expression with several clinical characteristics, as well as different tumour subtypes." (PMID 19099573, 2008). "However, most ER-positive tumours have low EZH2 and the reported corepressor for EZH2 is downregulated in high-grade tumours, where EZH2 expression is high." (PMID 19099573, 2008). "Most importantly, these T cells can recognize endogenously processed antigen and are cytotoxic against tumour cell lines naturally expressing EZH2, suggesting that PcG proteins are a novel group of TAA with potential as antigens for immunotherapy in a wide range of cancers." (PMID 17024127, 2006). "It was encouraging that T cells cloned in response to an EZH2-derived peptide could recognize endogenously processed and presented antigen, suggesting that EZH2-specific T cells would be able to recognize and kill tumour cells." (PMID 17024127, 2006). "Furthermore, EZH2 gene-expression levels in tumour tissue specimens (0.34±0.52) were significantly higher (P<0.0001) than those in the corresponding nontumour tissue specimens (0.07±0.09)." (PMID 15856046, 2005). "The question naturally arises whether EZH2 actually contributes to tumour development or whether it is just a biomarker of tumour progression." (PMID 15856046, 2005). "Thus, exploring the distinct changes in the tumor microenvironment (TME) triggered by EZH2 inhibition could provide valuable insights for strategically combining different immunotherapies." (PMID 41226368, 2025). "In different tumor types, the epigenetic modifications induced by CAFs in tumor cells have been analyzed, such as in ovarian cancer cells, where it was observed that CAFs prompt EZH2 histone methyltransferase upregulation, which results in cancer cell migration and increased invasion." (PMID 41514582, 2025).
tumor (continued). "We specifically examined the association between EZH2 expression and 10 key clinicopathological features of HCC, including patient demographics (age and sex), tumor stage (T, N, M), pathological stage, presence of residual tumor, histological grading, and OS events." (PMID 41298718, 2025). "In addition, our study investigated the anti-tumor effect induced by the interaction of immune cells within mouse model when simultaneously treating with the EZH2 degrader and the immune checkpoint inhibitor, anti-PD-1, and elucidating the underlying mechanisms." (PMID 40308579, 2025). "In conclusion, EZH2 is involved in a wide range of tumor biological behaviors, including promoting the survival and proliferation of cancer cells, promoting the migration and invasion of cancer cells, playing a key role in drug resistance in cancer cells, and regulating tumor immunity." (PMID 40028035, 2025). "Moreover, the epigenetic regulator EZH2 plays a dual role in immune escape: intrinsically, by suppressing genes essential for T cell activation; and extrinsically, by promoting the accumulation of immunosuppressive cells in the tumor microenvironment." (PMID 41050070, 2025). "To verify whether monocyte- and macrophage-CM modulate the tumor plasticity of SCC cells, we analyzed the expression of genes associated with epithelial-mesenchymal transition (EPCAM, SOX2), stemness (NANOG, MYC, EZH2), and neuroendocrine differentiation (CHGA, AURKA, MYCN)." (PMID 41259557, 2025). "Furthermore, IHC staining confirmed the reduced EZH2 expression in Usp22-null tumor cells." (PMID 41252204, 2025). "Our molecular docking analysis, which demonstrated strong binding between PCBs and EZH2, hypothesizes that PCBs exposure could potentially influence EZH2’s oncogenic activity, possibly leading to epigenetic modifications that promote tumor growth and therapy resistance." (PMID 40584614, 2025). "EZH2 may serve as an independent prognostic biomarker in HCC, with its expression associated with inverse methylation patterns at specific CpG sites, cg08558971 and cg18416251 across different tumor stages." (PMID 41209556, 2025). "For example, EZH2 might facilitate tumor immune evasion by T-cell exclusion and dysfunction." (PMID 40701777, 2025). "While EZH2 inhibitors like tazemetostat have shown promise in clinical trials, their effectiveness in GBM remains inconsistent, since prolonged inhibition of EZH2 in GBM cells has been linked to tumor progression due to activation of cell proliferation and DNA damage repair pathways." (PMID 40565099, 2025). "Therefore, targeting EZH2 will become an effective anti-tumor strategy." (PMID 40028035, 2025). "Furthermore, tumor cell metabolism is a hot topic in recent years, and whether SETD2 or EZH2 influence tumor cell metabolism and its corresponding mechanism needs to be studied." (PMID 40959108, 2025). "These intrinsic events within tumor cells enhance ER stress‐associated ubiquitylation and degradation by triggering ubiquitin via the E1 activase UBA6, facilitating ubiquitin transferring to E2 conjugate UBE2Z and increasing the activities of E3 ligase FBXW7 to degrade both EZH2 and MYC." (PMID 39823459, 2025). "Also, the complex role of EZH2 in the tumor microenvironment may explain its unsatisfactory clinical benefits." (PMID 40028035, 2025). "In AML, some studies also suggested that EZH2 may act as a tumor suppressor." (PMID 39655332, 2024). "EZH2 inhibitors may modulate tumor immunogenicity and anti-tumor immune responses." (PMID 38491228, 2024).
tumor (continued). "Future studies will focus on understanding whether T-cell activation and subsequent IFNγ signaling are major drivers of increased MHCI and MHCII on tumor cells in vivo, and whether cells other than T cells, such as neutrophils, are required for tumor stasis in response to EZH2 inhibitor." (PMID 38265267, 2024). "Moreover, it has been reported that EZH2 might increase tumor stemness and metastasis capacity and inhibit antitumor immunity by affecting T cells, NK cells, macrophages, and immune checkpoints." (PMID 38882008, 2024). "On the other hand, EZH2 may work independently of PRC2 as a co-activator to enhance tumor growth." (PMID 38911968, 2024). "Moreover, the combination of SGC0946 and GSK343 significantly reduced tumour growth in comparison to single agent therapy, suggesting combined inhibition of EZH2 and DOT1L may represent an effective therapeutic approach for NB patients." (PMID 39501501, 2024). "Notably, the EZH2 expression pattern in tumor tissues was similar to that of SIRT7, suggesting that only the shRNA EZH2 lentivirus treatment could alter the EZH2 expression levels." (PMID 39719443, 2024). "Interestingly, EZH2 inhibitors resulted in an elevation of MDSCs within the tumor microenvironment." (PMID 38600608, 2024). "A tumor marker with such potential could be the Enhancer of Zeste Homolog 2 protein (EZH2)." (PMID 40135141, 2024). "Moreover, recent studies have shown that IFN-γ could stimulate galectin-9 expression in tumour and immune cells via EZH2." (PMID 38166741, 2024). "Therefore, the regulation of EZH2 to promote tumor immunity is multi-mechanism and multi-pathway." (PMID 39227959, 2024). "It remains to be seen whether EZH2 promotes metastasis in the same manner across tumor types." (PMID 38886296, 2024). "EZH2-mediated DNA methylation associated with DNMT1 and H3K27me3 may inhibit the expression of the type 1 T helper cell (TH1) chemokines CXCL9 and CXCL10, as well as the subsequent transport of effector T cells to the tumor microenvironment." (PMID 38665224, 2024). "Moreover, the upregulation of miR26a could restore Enz sensitivity in vitro and in vivo, synergistically suppressing tumor growth, bone metastasis, and secondary metastasis by regulating the EZH2/SFRP1/WNT5A axis." (PMID 38566211, 2024). "Collectively, these results demonstrate that SMA+ fibroblasts contribute to SASP and NK and T cell suppression in the pancreas TME, and suggest that this may be mediated in part through EZH2-driven transcriptional repression of inflammatory signaling in tumor cells." (PMID 37142692, 2023). "We may be inspired by studies that have achieved some results, such as combining EZH2 inhibitors with immunotherapy, chemotherapy, targeted therapy, endocrine therapy, and other therapies that may achieve complementary or synergistic anti-tumor effects." (PMID 36672374, 2023). "Thus, targeting EZH2 may contribute to the synergistic anti-tumor efficacy of senescence induction therapies and immunotherapies." (PMID 38008711, 2023). "Other than CDK4 inhibition, we also found some reported or new tumor suppressor genes that may potentially regulated by EZH2 degradation induced by IHMT-337 in our transcriptomic data, suggesting IHMT-337 induced degradation of EZH2 results in complicated transcriptional regulation." (PMID 36642705, 2023). "Indeed, it is important to note that SW1736 cells show high levels of PAX8, FOXE1 and CDH1, compared to KTC2, indicating ATC tumor heterogeneity that may influence the response to EZH2 modulation." (PMID 37175580, 2023). "Besides, inhibiting the transcription of many genes, EZH2 has also been presented to suppress the expression of many tumor suppressor microRNAs (miRNAs), such as miR-125a, miR-125b, miR-138-5p, and miR-320c in HCC, thus assisting HCC tumorigenicity and metastasis." (PMID 37689710, 2023). "Thus, the features of each tumor should be considered in the application of EZH2 inhibitors." (PMID 38036730, 2023).